IGKV1-37 (immunoglobulin kappa variable 1-37 (non-functional))
Description:
Probable non-functional open reading frame (ORF) of V region of the variable domain of immunoglobulin light chains. Non-functional ORF generally cannot participate in the synthesis of a productive immunoglobulin chain due to altered V- (D)-J or switch recombination and/or splicing site (at mRNA level) and/or conserved amino acid change (protein level). Immunoglobulins, also known as antibodies, are membrane-bound or secreted glycoproteins produced by B lymphocytes. In the recognition phase of humoral immunity, the membrane-bound immunoglobulins serve as receptors which, upon binding of a specific antigen, trigger the clonal expansion and differentiation of B lymphocytes into immunoglobulins-secreting plasma cells. Secreted immunoglobulins mediate the effector phase of humoral immunity, which results in the elimination of bound antigens. The antigen binding site is formed by the variable domain of one heavy chain, together with that of its associated light chain. Thus, each immunoglobulin has two antigen binding sites with remarkable affinity for a particular antigen. The variable domains are assembled by a process called V-(D)-J rearrangement and can then be subjected to somatic hypermutations which, after exposure to antigen and selection, allow affinity maturation for a particular antigen.
Synonyms: IGKV137; O14
Gene: Immunoglobulin variable (V) gene on chromosome 2 (89,297,264 to 89,297,785, reverse strand). Ensembl gene ENSG00000239862.
Subcellular location: Secreted; Cell membrane
Gene Ontology:
Biological process: immune response
Cellular component: extracellular region; immunoglobulin complex; plasma membrane
Homologues: Orthologues: mouse Igkv15-103 (70% identical). Paralogues in human: IGKV1D-37 (100% identical), IGKV1-27 (87% identical), IGKV1-39 (87% identical), IGKV1D-39 (87% identical), IGKV1-9 (86% identical), IGKV1D-13 (85% identical), IGKV1-12 (85% identical), IGKV1-6 (85% identical), IGKV1-33 (84% identical), IGKV1D-12 (84% identical), IGKV1D-33 (84% identical), IGKV1D-16 (83% identical), and 81 more.
Diseases named in the same sentence as IGKV1-37 in open-access papers:
IGKV1-37 is named in the same sentence as 1 disease in open-access papers, as found by Europe PMC text mining. Sharing a sentence is not in itself a finding about the gene and the disease.
IGKV1-37 shares sentences with these, for which no sentence is quoted: infection (1 paper).